TRIM25 (tripartite motif containing 25)
Diseases named in the same sentence as TRIM25 in open-access papers (continued):
Sharing a sentence is not in itself a finding about the gene and the disease.
viral infection (continued). "Thus, RIG-I- and TRIM25-mediated rapid production of type I IFN is facilitated by USP15 to fight against virus infection." (PMID 33946990, 2021). "MEX3C, TRIM4 and TRIM25 are the most important E3 ligases for positive regulation of RIG-I activity in response to viral infection, whereas RNF122 and RNF125 have been described to mediate the ubiquitin-dependent degradation of this cytosolic innate immune receptor." (PMID 32019099, 2020). "Knockout of TRIM25 severely reduced RIG-I-mediated type I IFN production during viral infection." (PMID 29354136, 2017). "For example, TRIM25 polymorphisms have been associated with differences in the humoral response and secretion of some cytokines following measles virus vaccination in children; and particular virus infections of mice also suggest a role of TRIM25 in regulating RIG-I in vivo." (PMID 29018447, 2017). "TRIM25 functions as an ubiquitin E3 ligase, and has been implicated in the regulation of innate immunity by mediating ubiquitination of RIG-I (Retinoic-acid-inducible gene-I), a protein involved in interferon synthesis in response to viral infection." (PMID 27626314, 2016). "Interestingly, a recent study has suggested that TFG binds TRIM25 upon viral infection and negatively regulates RIG-I-mediated type I IFN signalling." (PMID 24999993, 2014). "Crucially, individual IAV mRNAs can associate with a plethora of other factors that could contribute or impede TRIM25 function, which might explain large variation in the obtained results, and warrant further investigations into the RNA-directed role of TRIM25 in viral infections." (PMID 35736141, 2022). "The E3 ligase tripartite motif protein 25 (TRIM25)-mediated attachment of Lys63-linked ubiquitin chains activates the viral sensor, a retinoic acid-inducible gene I (RIG-I), resulting in the stimulation of the production of the cytokines IFN-α and IFN-β upon viral infection." (PMID 33946990, 2021). "Notably, Mx and TRIM25 were significantly up-regulated against viral infection." (PMID 27916934, 2016). "MiR-30a is upregulated by coxsackievirus B3 (CVB3), inhibiting TRIM25 expression and subsequent RIG-I ubiquitination, which facilitates CVB3 replication and enhances viral infection." (PMID 40431746, 2025). "It was further found that the CSFV NS4A protein interacts with the E3 ubiquitin ligase TRIM25 and is targeted to mediate the autophagic degradation of RIPK3, thereby blocking the progression of necroptosis to achieve persistent viral infection." (PMID 38100396, 2024). "Upon viral infection, the retinoic acid-inducible gene I (RIG-I), responsible for recognizing viral RNA, is ubiquitinated by the tripartite motif-containing protein 25 (TRIM25)." (PMID 37764153, 2023). "TRIM25, for example, which is known to help increase RIG-I signaling during viral infection in mammals and ducks, had much less relative expression in brain." (PMID 37622121, 2023). "On the one hand, TRIM25 positively regulates the innate immune response by targeting RIG-I and MDA5 during virus infection." (PMID 37628607, 2023). "In response to various viral infections, the active RIG-I attaches to K63-polyubiquitin chains, which are synthesized by TRIM25, to promote the transcriptional upregulation of IFNs." (PMID 37391858, 2023). "TRIM25 has been shown to play a role in the retinoic-acid-inducible gene-1 (RIG-I) pathway, which triggers expression of type 1 interferons upon viral infection." (PMID 35736141, 2022). "Upon viral infection, CARD in RIG-I is exposed, allowing itself to interact with tripartite motif-containing protein 25 (TRIM25) and mitochondrial antiviral signaling gene (MAVS)." (PMID 36439216, 2022). "TRIM25 has been shown to play a role in the retinoic-acid-inducible gene-1 (RIG-I) pathway, which triggers expression of type I interferons upon viral infection." (PMID 35736141, 2022).
viral infection (continued). "The interactions of TRIM25 and ZAP during viral infection and the effect on the stability of viral mRNAs and virus replication needs to be further investigated." (PMID 35736141, 2022). "Ubiquitin-specific protease 15 interacted with and deubiquitylated TRIM25, thereby promoting RIG-I-mediated antiviral signaling during viral infection." (PMID 32120903, 2020). "In agreement with the role of H3K79 methylation in viral infection, alterations in RUBCN, TRIM25 and BCL3 gene expression in DOT1L down-regulated cells were found." (PMID 31727944, 2019). "During the course of viral infection, the NS1 protein of IAV inhibits host IFN responses either by sequestering viral dsRNA or by binding to RIG-I and TRIM25 or RIPLET proteins required for RIG-I activation and IFN signaling pathways." (PMID 28717359, 2017). "IFNα and IFNγ, two types of antiviral cytokines, were also up-regulated after viral infection, activating the JAK-STAT signaling pathways and inducing the transcription of ISGs, including Mx, OASL2, GBP, IFIT5, and TRIM25." (PMID 27916934, 2016). "To this end, we silenced endogenous TRIM25 in chicken LMH cells and measured IFN-β mRNA expression upon viral infection." (PMID 23209422, 2012). "Among these, several are known or suspected to be involved in defending the cell against viral infection, including TRIM5, TRIM19, TRIM25 and TRIM28." (PMID 18389077, 2008). "The TRIM25 gene is a kind of interferon-stimulated gene (ISG) whose promoter can be activated by type I interferon (IFN1α and IFNβ), and its expression is induced during viral infection." (PMID 40431746, 2025). "We thus speculate that TRIM25 might have other RING and RBD-independent functions that are crucial for its role in inhibiting viral infection." (PMID 35736141, 2022). "We validated most of the TRIM25-R54P interactors that are not present on the TRIM25-WT lists in the absence or presence of viral infection." (PMID 36067236, 2022). "We examined whether TRIM47 undergoes ubiquitination when Tim-3 is overexpressed, as TRIM25, an E3 ligase with a structure similar to TRIM47, undergoes ubiquitination during viral infection." (PMID 34110282, 2021). "The significant downregulation of interferon signature genes, such as Adar (DRADA), Ddx58 (RIG-I), Ddx60 (DDX60), Stat1 (STAT1), Ifih1 (MDA5), Trim25 (TRIM25), Irf7 (IRF7), and Irf9 (IRF9) in infected Cd47−/− NK cells is consistent with the impaired Cd47−/− NK cell response to viral infection." (PMID 30643501, 2018). "Since several studies have shown that TRIM25 migrates to the mitochondria upon viral infection to interact with MAVS, the interaction between MAVS and NS1 might be a result of the interaction between NS1 and TRIM25." (PMID 30558248, 2018). "As for DDX58, NFκB1, TOLLIP, RIPK1, DDX3Y, TRIM25 and JAK2, which are involved in antiviral signalling transduction, both increased mRNA abundance and switched poly(A) sites eventually led to enhanced protein production following viral infection." (PMID 28233779, 2017). "The induction of a number of cytokines was also abolished in Riplet−/− but not Trim25−/− or Mex3c−/− cells on virus infection." (PMID 28469175, 2017). "Thus, the TRIM25-mediated ubiquitination pathway and the RIG-I antiviral pathway are a complex and sophisticated regulatory network that ensures that the host is able to rapidly and efficiently initiate an immune response against viral infection." (PMID 40170840, 2025). "To test whether viral infection promotes the co-localization of TRIM25 and these AVPs, we examined the subcellular localizations of G3BP1, TRIM25 and multiple AVPs in TRIM25 KO HeLa cells that were rescued with GFP-TRIM25 WT or ∆PTFG." (PMID 38750080, 2024). "The protein levels of TRIM25 may also have to be at a certain level in order for it to productively ubiquitinate RIG-I, as the ubiquitin protease USP15 deubiquitinates TRIM25 at later time points in viral infection." (PMID 31379819, 2019).
viral infection (continued). "Hence, SGs serve as a platform for many antiviral actions because they contain many regulatory proteins, including TRIM25 and G3BP1/2, and the NP of SARS-CoV-2 and the H1N1 NS1-A protein can interfere with their recruitment and thus inhibit antiviral responses during corresponding viral infections." (PMID 40431746, 2025). "Hence, these results indicate that in mammalian cells TRIM25 is recruited into stress granules upon stimulation of the innate immune response ether by transfection-based plasmid overexpression or virus infection, where it interacts with RIG-I, but not with MAVS." (PMID 36519174, 2022). "Viral infection induces the formation of avSGs, including conventional SG markers, RIG-I, MDA5, LGP2, PKR, OAS, RNase L, DHX36, TRIM25, PUM1 and PUM2, some of which are critical in sensing non-self viral RNA and triggering antiviral signaling." (PMID 25340845, 2014). "However, although NS1 proteins from several IAV strains bind to TRIM25, not all of these are capable of inhibiting phosphorylation of IRF-3 (presumably following RIG-I activation) upon virus infection." (PMID 35736141, 2022).
breast carcinoma (35 papers, 2016 to 2025). "TRIM25 constitutes a key regulator of metastatic gene signatures in breast cancer and elevated TRIM25 mRNA is associated with poor prognosis in breast cancer and several other cancers." (PMID 35935998, 2022). "TRIM25 is reported to be upregulated in endometrial cancer, ovary cancer, prostate cancer, lung cancer and breast cancer and its overexpression is associated with poor prognosis, at least for breast cancer patients." (PMID 33670160, 2021). "Containing a hallmark zinc-finger B-box DNA-binding domain, TRIM25 has been shown to function as a transcriptional suppressor in a signal network promoting breast cancer metastasis." (PMID 32826889, 2020). "The functional relevance of TRIM25 during denervation remains largely unknown, although TRIM25 has been linked to breast cancer growth." (PMID 28546288, 2017). "Mechanistically, TRIM25-associated drug resistance was linked with downregulation of the scaffold protein 14-3-3σ, which itself is a known target of TRIM25-dependent proteasomal degradation in breast cancer by depending on the ubiquitin conjugating enzyme UbcH8." (PMID 39851496, 2025). "In a word, the TRIM25/BRD7 signaling axis is indeed related to the paclitaxel resistance in breast cancer." (PMID 41315221, 2025). "To further reveal the mechanism of BRD7’s involvement in development and PTX chemotherapy sensitization in breast cancer, we screened and identified a potential E3 ubiquitin ligase, TRIM25, interacting with BRD7 by IP-MS in our previous study." (PMID 41315221, 2025). "Nevertheless, the functions and mechanisms of TRIM25 in the malignant progression of breast cancer and PTX resistance, as well as its regulatory relationship with BRD7, are still not clear." (PMID 41315221, 2025). "Next, we analyzed the correlation between TRIM25 expression and prognosis of breast cancer patients treated with PTX, and found that the breast cancer patients treated with PTX with lower expression of TRIM25 had a longer overall survival." (PMID 41315221, 2025). "In order to further confirm the important role of the TRIM25/BRD7 axis in paclitaxel resistance of breast cancer, we detected the differential expression of TRIM25 and BRD7 between PTX-resistant BC cells and their parent cells." (PMID 41315221, 2025). "Our results confirmed that TRIM25 was highly expressed in breast cancer tissues, and its high expression was positively correlated with advanced clinical stages and poor survival in BC patients." (PMID 41315221, 2025). "The combination of RIG-I and TRIM25 can predict the prognosis of breast cancer patients with estrogen receptor-positive, and the high expression of TRIM25 is related to the poor prognosis of patients with gastric cancer." (PMID 41315221, 2025). "Collectively, these results demonstrate that TRIM25 plays a critical role in conferring resistance to paclitaxel in breast cancer cells." (PMID 41315221, 2025). "Taken together, these results indicate that TRIM25 directly interacts with BRD7 in breast cancer cells." (PMID 41315221, 2025). "For example, TRIM25 mediates the degradation of ATBF1 protein induced by estrogen, promoting the proliferation of breast cancer cells, and TRIM25 also degrades 14-3-3σ protein, promoting tumor growth in breast cancer." (PMID 41315221, 2025). "This study supports the concept of employing chimeric TRIM25-specific chimeric siRNA as a useful treatment alternative in breast cancer therapy." (PMID 39851496, 2025). "The results of IHC showed that the expression level of TRIM25 in breast cancer tissues was significantly higher than that in normal breast tissues." (PMID 41315221, 2025).
breast carcinoma (continued). "The Cell Counting Kit-8 (CCK-8) assay was performed to explore the effect of TRIM25 on the proliferation of breast cancer cells." (PMID 41315221, 2025). "Taken together, these data validate that TRIM25 promotes breast cancer tumorigenesis and PTX chemotherapy resistance by negatively regulating the stability of BRD7 protein in vivo." (PMID 41315221, 2025). "Elevated TRIM25 is associated with the progression of several types of cancer, and its upregulation correlates with poor prognosis in HCC, breast cancer, and glioma." (PMID 40096176, 2025). "In the present study, we revealed the important role of TRIM25 in promoting PTX-mediated chemotherapy resistance in breast cancer, demonstrated both in vitro and in vivo." (PMID 41315221, 2025). "In order to further substantiate that TRIM25 was indeed related to paclitaxel resistance in breast cancer cells, a paclitaxel-resistant MDA-MB-231 cell line (MDA-MB-231-PR) was used for the following study." (PMID 41315221, 2025). "IGF2BP3 and miR-3614-3p can competitively bind TRIM25 mRNA, thus protecting TRIM25 mRNA from degradation and promoting breast cancer cell proliferation." (PMID 37298373, 2023). "TRIM25 is overexpressed in multiple malignancies, including breast cancer, lung cancer, liver cancer, colorectal cancer, prostate cancer, and ovarian cancer." (PMID 36199797, 2022). "Studies have found that TRIM25 is involved in the development of prostate cancer, endometrial cancer, ovarian cancer, breast cancer and other cancers." (PMID 33858324, 2021). "Survival analysis found APP, TRIM25 and ELAVL1 to have significant associations with overall survival (log-rank p-value <0.05) in breast cancer." (PMID 34193143, 2021). "Downregulation of TRIM25 inhibits proliferation of breast cancer cells and tumor growth in vivo and migration and invasion of lung and gastric cancer cells." (PMID 33670160, 2021). "Degradation of CIC protein following loss of ATXN1L was instead observed to be mediated by the E3 ubiquitin ligase TRIM25 which was further validated using glioma-derived cell lines and the TCGA breast carcinoma and liver hepatocellular carcinoma cohorts." (PMID 33115448, 2020). "Utilizing previously published gene expression data and TCGA cohorts, TRIM25 amplification in breast carcinoma was found to dysregulate several shared gene sets, related to cell growth and proliferation, with CIC loss." (PMID 33115448, 2020). "In contrast to normal adjacent tissues, TRIM25 mRNA levels were found notably upregulated in several cancerous tissues including liver cancer, breast cancer and low grade glioma." (PMID 31953436, 2020). "By employing chromatin immunoprecipitation sequencing (ChIP-seq) and gene set enrichment analysis, TRIM25 was identified as an important transcriptional regulator of breast cancer metastasis." (PMID 33066016, 2020). "It is noteworthy that TRIM25 was shown to serve as a specific ligase for 14-3-3σ and promote its proteasomal degradation in breast cancer cells." (PMID 29357390, 2018). "TRIM25 has an elevated expression in breast cancer and ovarian cancer, but down-regulated in the endometrial carcinoma." (PMID 28620119, 2017). "TRIM25 has a strong connection with different types of cancers, including breast cancer, ovarian cancer, endometrial cancer, lung cancer, and gastric cancer." (PMID 28620119, 2017). "It has been reported that TRIM25 has an elevated expression in breast cancer, ovarian cancer, lung cancer, and gastric cancer, but down-regulated in the endometrial carcinoma." (PMID 28620119, 2017). "For example, we previously showed that TRIM25/Efp (estrogen-responsive finger protein) plays an oncogenic role in breast cancer by functioning as an E3 ubiquitin ligase that degrades cell cycle checkpoint 14-3-3σ." (PMID 28885545, 2017). "TRIM25 has also been shown to be regulated by estrogen receptor alpha in breast cancer and to mediate ubiquitination and degradation of two transcription factors: KLF5 and ZFHX3." (PMID 27626314, 2016).